CD47 (CD47 molecule)
Diseases named in the same sentence as CD47 in open-access papers (continued):
Sharing a sentence is not in itself a finding about the gene and the disease.
tumor (continued). "RAGA deficiency promotes tumor growth due to the accumulation of CD47, which sensitizes the tumor to CD47 blockade." (PMID 36823443, 2023). "High expression of CD47 in tumor cells has frequently been associated with poorer prognosis across many types of cancers." (PMID 37012357, 2023). "Tumor cell-associated CD47 has been shown to promote proliferation, metastatic potential, and drug resistance, and regain tumor-initiating ability and EMT." (PMID 37063284, 2023). "To identify the mechanism associated with this increased inflammation, we observed that tumor-promoting genes such as CD47, TGFB1, and NKFB1 are linked with Kaiso expression in AA patients." (PMID 37190208, 2023). "Tumor and atherosclerotic necrotic cores increase the expression of CD47 and prevent efferocytosis, thereby causing disease progression." (PMID 37368493, 2023). "After that, the molecular mechanisms underlying the role of the CD47–SIRPα axis in normal and tumor tissues are gradually clarified." (PMID 36939440, 2023). "This phenomenon has been observed in many tumor cells, e.g., the increased expression of CD47 is associated with poor prognosis in leukemia." (PMID 37375166, 2023). "Compared with KRASWT tumors, the tumor samples with KRAS mutations displayed higher expression of CD47 and p-STAT3." (PMID 36413402, 2023). "The present study focused on the CD47 molecule, which is associated with macrophages and tumor immunity." (PMID 37545625, 2023). "The use of anti-CD47 mAbs reduces CD47/SIRPα cross-talk, thereby causing macrophages to phagocytose tumor cells." (PMID 38033495, 2023). "SIRPα is a transmembrane glycoprotein specifically expressed on myeloid cells and provides a “do not eat me” signal after engaged with integrin‐associated protein CD47 on tumour cells." (PMID 36419386, 2023). "Exosomes with SIRPα on their surface have been constructed capable of preventing CD47-SIRPα interaction between cancer cells and macrophages, causing tumor growth to regress." (PMID 37373342, 2023). "The association among CD47 and the tumor microenvironment was assessed utilizing the TISCH single cell data database." (PMID 37719086, 2023). "Elevated expression of CD47 in some cancers is associated with poor survival related to its function as an innate immune checkpoint when expressed on tumor cells." (PMID 36768931, 2023). "And it has been proved that CD47 blockade can also enhance tumor cell phagocytosis by tumor-associated macrophages (TAMs)." (PMID 37171006, 2023). "Bromonitrozidine (RRx-001) is a minimally toxic, NLRP3 inhibitor that has been observed, in experimental systems, to also downregulate CD47, repolarize tumor associated macrophages (TAMs) and normalize aberrant tumor perfusion." (PMID 36960054, 2023). "CD47 is known to be increased in a number of cancers, making tumor cells less susceptible to phagocytosis." (PMID 37020553, 2023). "A similar study in 328 colorectal adenocarcinomas treated with surgery demonstrated the overexpression of CD47 in 16% of patients, which was associated with node involvement, tumor budding and poor recurrence-free survival." (PMID 37232754, 2023). "Interaction of tumour PD‐L1 with PD‐1 on tumour infiltrating lymphocytes (TILs) and tumour CD47 with SIRPα on tumour‐associated macrophages (TAMs) have been recognised as a major mechanism of tumour immune evasion." (PMID 37974395, 2023). "designed another PD-L1/CD47 bispecific antibody, namely BisAb, which exhibited a high affinity for PD-L1, thereby enhancing tumor exposure and reducing the risk of anemia." (PMID 37313405, 2023). "Our results reveal a direct mechanistic link between active KRAS and innate immune evasion and identify CD47 as a major effector underlying the KRAS-mediated immunosuppressive tumor microenvironment." (PMID 36413402, 2023). "Secondly, blocking the CD47/SIRPα axis can transform tumor-associated macrophages into an antitumor state, and increase tumor macrophage recruitment." (PMID 36726125, 2023).
tumor (continued). "This suggests that inhibiting CD47 efficiently causes the diverse macrophage population seen in in vivo studies to start destroying tumor cells." (PMID 38033495, 2023). "Upregulation of CD47 on cancer cells has consistently been associated with immune evasion, tumor progression, and poor prognosis." (PMID 38188674, 2023). "In EC, CD47 acts as an antiphagocytic signal that promotes tumor resistance against tumor-associated macrophages, and CD47 blockade increased the infiltration of macrophages in vivo and promoted phagocytosis of EC cells by M2 macrophages." (PMID 37368179, 2023). "Our previous study identified several regulators of CD8 T cell function for which protein expression was regulated by loss of CD47 expression in the tumor microenvironment, including TIGIT, PD-1, CD39, CD62L, and CD127." (PMID 36768931, 2023). "Here, we observed that there was an association between CD47 and TGFβRI, both being used by tumor cells for evasion of the immune system." (PMID 37569332, 2023). "Cd47 knockdown induced phagocytosis and antigen presentation, and knockdown of Cd274 and Mcl1 reduced checkpoint inhibition and caused tumor cell death, respectively." (PMID 36969696, 2023). "CD47, as the integrin-associated protein, is overexpressed on tumor and SARS-CoV-2-infected cells as a potential surface biomarker for immune surveillance evasion." (PMID 37456027, 2023). "That study also demonstrated that preventing CD47/SIRPα cross-talk causes a variety of polarized macrophages to engulf tumor cells and that this action is necessary for producing FcγRs." (PMID 38033495, 2023). "Researchers have also investigated using anti-CD47 monoclonal antibodies to reprogram the tumor-associated macrophages in the microenvironment." (PMID 37987252, 2023). "High CD47 expression in the tumor microenvironment has also been associated with poor patient prognosis in various cancer types." (PMID 36413402, 2023). "We uncover RAGA as a CD47 negative regulator by promoting its lysosome degradation, thus suppressing tumor growth and serves as a potential diagnostic marker of cancer malignancy." (PMID 36823443, 2023). "Third, anti-CD47 has been shown to synergize with trastuzumab monoclonal antibody, augment tumor associated macrophages and phagocytosis as well as antibody-dependent cellular cytotoxicity (ADCC) activity." (PMID 37468567, 2023). "CD47 is a transmembrane protein expressed in multiple tumor types and linked to many pathophysiological processes." (PMID 36670786, 2023). "RRx-001 is a minimally toxic NLRP3 inhibitor in Phase 3 for small cell lung cancer (SCLC) that is associated with vascular normalization properties as well as epigenetic inhibition and tumor associated macrophage repolarization through CD47 downregulation." (PMID 36960054, 2023). "Subsequently, the combined CRT over-expression and CD47 low-expression on the tumor cell plasma membrane cooperatively activate the anti-tumor effect of TAMs and induce DCs to capture tumor-associated antigens and present them to T cells." (PMID 37951973, 2023). "CD47 is identified as an integrin‐associated protein on tumor cells and binds to signal regulatory protein alpha (SIRPα) on phagocytes, such as macrophages." (PMID 36598153, 2023). "CD47 knockout increased tumor-associated extracellular matrix protein tenascin C (TNC) in U87 intracranial xenografts." (PMID 35967394, 2022). "Further analysis of the association between the Tumor Recurrence Factor risk score and common immune checkpoints of tumors showed that the Tumor Recurrence Factor risk score was correlated with CD47, CTLA7, HAVCR2, LAG3, PDCD1, and other immune checkpoints." (PMID 35677036, 2022). "Overexpression of CD47 by tumor cells causes an inhibitory effect on myeloid cells such as macrophages." (PMID 35954362, 2022).
tumor (continued). "CD47 serves as a tumor-associated cell surface recognition protein and is associated with chemoresistance, while tumor hypoxia and HIF-1 are involved in indirectly activating the translation of CD47 to induce the mechanism of immune evasion in tumors." (PMID 36233088, 2022). "Mechanistically, local administration of Bifidobacteria triggered the STING signaling and promoted cross-priming of tumor-associated DCs post anti-CD47 therapy." (PMID 36726985, 2022). "In some human cancers, CD47 binds to SIRPA to trigger the inhibitory signaling pathway that caused tumor cells to evade from phagocytosis by macrophages." (PMID 35211415, 2022). "Remarkably, previous studies have shown that a high CD47 expression on tumor cells is associated with poor prognosis in both hematological and solid cancers." (PMID 35538512, 2022). "The low-affinity binding to CD47 and the associated increased tumor selectivity results in a higher safety profile of the described bsAbs." (PMID 35479092, 2022). "In particular, CD47 is an immune checkpoint molecule that can inhibit phagocytosis of cancer cells by tumor-associated macrophages (TAMs), and CD47 blockade has been found to synergize with chemotherapy cabazitaxel in preclinical models of TNBC." (PMID 35856032, 2022). "Linear regression analysis revealed a direct association between CD47 expression by cancer cells and SIRPαΜφ-score (p = 0.0008, r = 0.33 for both the invading front and inner tumor areas)." (PMID 35406573, 2022). "In the late 2000s, the cross talk of CD47/SIRPα was recognized as the first checkpoint associated with tumor phagocytosis (also known as a “don’t eat me” signal)." (PMID 35978372, 2022). "Different from B7-H3, which can be considered a tumor-associated antigen, CD47 is overexpressed by many types of tumors but is also widely expressed in normal cells." (PMID 35205760, 2022). "As a result, the promotion of CCR9+CD8+ T-cell infiltration enhanced the antitumor effect induced through the downregulation of CD47 expression and caused tumor growth arrest and the inhibition of metastatic dissemination." (PMID 35335881, 2022). "These tumor cells have also over expressed on surface the integrin associated protein (CD47), involved in protection against to macrophages of the immune system." (PMID 36555827, 2022). "Our study showed that COAD, HNSC, KICH, STAD, and THCA tumor tissues expressed high levels of CD47, and high expression of CD47 in tumor tissue was associated with worse OS in PAAD." (PMID 36059952, 2022). "High CD47 expression was significantly associated with the presence of ulceration (p = 0.019) and larger tumor size (p = 0.004) in SCC." (PMID 36010209, 2022). "CD47 (Cluster of Differentiation 47) is an integrin-associated protein that is overexpressed by tumour cells and TEV and plays a role in immune regulation." (PMID 36011012, 2022). "High CD47 expression showed a significant association with the presence of ulceration (p = 0.019) and larger tumor size (p = 0.004)." (PMID 36010209, 2022). "Immunotherapies targeting the “don’t eat me” myeloid checkpoint constituted by CD47 SIRPα interaction have promising clinical potential but are limited by toxicities associated with the destruction of non-tumor cells." (PMID 35795660, 2022). "Nowadays, substantial evidence supports that the checkpoint inhibitors of SIRPα-CD47 can suppress tumor growth by skewing tumor-associated macrophages toward the M1 phenotype from the M2 phenotype, which restores the phagocytic activities of macrophages." (PMID 36497444, 2022). "It has been established that c-Myc plays a fundamental role in building an immunosuppressive tumor microenvironment through the recruitment of tumor-associated macrophages or through the upregulation of the checkpoint proteins CD47 and PD-L1." (PMID 35806053, 2022).
tumor (continued). "A recent experimental study by Hutter and co-workers has indicated that tumour-associated microglia are capable of tumour cell phagocytosis in vivo if the immune evasion of tumour cells is blocked by a humanized anti-CD47 monoclonal antibody." (PMID 36555253, 2022). "An adaptive tumor immune resistance to CD47 immunotherapy is reported via suppressing radiation-associated tumor immunogenicity by hijacking caspase 9 signaling pathway." (PMID 35314680, 2022). "CD47 activation in immune cells has been linked to tumor immune evasion, decreased antigen-presentation cell function, and impaired effector functions of NK and T cells." (PMID 35164813, 2022). "Cell and animal studies revealed that downregulation of CD47 significantly suppressed the proliferation and metastasis of cancer cell lines and caused tumor reduction in heterotopic and orthotopic xenograft mouse models." (PMID 35281519, 2022). "In the first pathway, anti-CD47 antibody disrupts anti−engulfment signal, promoting M1/M2 macrophages-mediated phagocytosis and shifting the immunosuppressive phenotype of tumor-associated macrophages (TAMs) toward M1 subtype in vivo." (PMID 35860564, 2022). "This indicates that tumor cells can avoid the effect of CALR through CD47, so as to prevent immune killing caused by physiologically dead tumor cells via CALR in the process of tumorigenesis." (PMID 36293504, 2022). "It has been proposed that the association between CD47 on tumor cells and thrombospondin-1 on T cells acts as an immunological checkpoint, impairing T cell activation and thereby decreasing antigen-dependent killing of tumor cells by CD8+ T cells." (PMID 35865547, 2022). "CDC50A loss-of-function increases the accumulation of chemotherapy drugs and tumour-associated macrophages and the effect of anti-CD47 blockade, limiting tumour growth." (PMID 35982417, 2022). "Up-regulated expression of CD47 was found in almost all types of tumor cells, which was associated with poor survival and prognosis." (PMID 34717710, 2021). "Recent studies have suggested the important roles of CD47 and tumor-associated macrophages in the prognosis and immunotherapy of various human malignancies." (PMID 33765961, 2021). "CD47, an integrin-associated protein that is overexpressed in malignant tumor cells, functions as an inhibitor of macrophage-mediated phagocytosis through the ligation of SIRPα." (PMID 33802565, 2021). "The tumor ECM was shown to be intricately linked to CD47-mediated macrophage phagocytosis signaling through the expression of tumor-associated extracellular matrix protein tenascin C (TNC)." (PMID 34571905, 2021). "Of interest, after TIS, binding of soluble TSP1 to CD47 causes emergence of tumor-resistant cells and metastasis in triple-negative breast cancer, and inhibits anti-melanoma NK cell activity with reduced granzyme B and IFNγ production." (PMID 34447383, 2021). "One arm often targets a tumor-associated antigen while the other targets an immune system-evading surface protein (such as CD47 or CD55/59), increasing susceptibility of the tumor cell to lysis by complement or NK cells, or phagocytosis by macrophages." (PMID 34069573, 2021). "Other techniques that use PCR or western blot or flow cytometry to detect CD47 proteins in tumor tissue and functional studies revealing association of tumor invasiveness with CD47 are required." (PMID 33917794, 2021). "Anti-CD47 antibodies block the inhibition of the phagocytic activity of macrophages caused by the up-regulation of CD47 on tumor cells." (PMID 33917174, 2021). "The physiopathological mechanism of this association appears intuitive, since higher levels of CD47 will more efficiently inhibit SIRPα on macrophages and therefore the tumor will evade innate immune response." (PMID 34195295, 2021).
tumor (continued). "Anti-MUC1 and anti-EGFR (cetuximab) antibodies have achieved effective antitumor effects in carcinoma A549 cancer cells, causing tumor regression by inhibiting the binding of SIRPα and CD47." (PMID 34683963, 2021). "CD47-SIRPα “don’t eat me” axis blockade has been proved so far to be a great success in mobilizing tumor-associated macrophages for tumor cell eradication." (PMID 33790906, 2021). "CD47 is involved in regulating tumor invasion and metastasis, and the underlying mechanisms have been extensively studied." (PMID 34363319, 2021). "The loss of CD47 function upregulates the tumor-associated extracellular matrix protein tenascin C (TNC) expression in tumor cells via a Notch pathway-mediated mechanism." (PMID 34071306, 2021). "These mutations drive B-cell lymphomagenesis and sensitize tumor cells to anti-CD47 “don’t eat me” blockage." (PMID 35083135, 2021). "Immune checkpoint molecules including B7-H3, CD47, and PD-L1, as well as tumor-infiltrating lymphocytes (TILs) and tumor-associated macrophages (TAMs), were manifested by immunohistochemical staining." (PMID 33815356, 2021). "First, most CD47-SIRPα studies are performed in immune-deficient mice, which hardly mimic macrophage activity or the tumor microenvironment." (PMID 34944878, 2021). "After anti-CD47 blockade, tumor-associated microglia was able to effectively phagocytize tumor cells." (PMID 32000794, 2020). "Efferocytosis induces conversion of tumor-associated macrophage to the M2 phenotype, which inhibits the clearance of ACs and promotes the expression of CD47 to escape from recognition." (PMID 32346605, 2020). "Several studies have reported the use of anti-CD47 in hematologic malignancies with promising results as anti-tumor therapy alone or in association with drugs used in clinical practice, including MM." (PMID 32899714, 2020). "Another route to target stem cells is through CD47 inhibition by RRx-001, which targets tumor-associated macrophages and CSCs via downregulation of the antiphagocytic CD47/SIRPα checkpoint axis." (PMID 32751469, 2020). "Taken together, these results indicate that CD11c+SIRPα+ DCs play an essential role in the antitumor responses induced by CD47-deficient tumor cell vaccination." (PMID 31996683, 2020). "The induction of antitumor responses depends on SIRPα+CD11c+ DCs, which exhibit rapid expansion following introduction of CD47-deficient tumor cells." (PMID 31996683, 2020). "Potent anti-tumor activities were associated with macrophage-mediated phagocytosis induced by HuNb1-IgG4, which is due to blockade of CD47/SIRPα." (PMID 31931812, 2020). "Multiple factors with varied cellular functions such as HER2 and CD47 are associated with the tumor acquired resistance." (PMID 32929084, 2020). "CD47 is a tumor-associated antigen best known for its ability to bind counter-receptors on the surface of professional phagocytes as an immune-evasion strategy." (PMID 33224442, 2020). "Our study highlights that CD47-deficient whole tumor cell vaccine is effective in eliciting antitumor immune responses." (PMID 31996683, 2020). "Tenascin C (an extracellular matrix protein) and hypoxia-inducible factor are also thought to mediate CD47-associated changes in the tumor microenvironment." (PMID 35582455, 2020). "CD47 is an independent risk factor for tumor prognosis, and inhibiting CD47 can enhance the antitumoral effect." (PMID 32733941, 2020). "CD47, a transmembrane integrin-associated protein, plays a key role in the ability of tumor cells to escape phagocytosis, working as an immune checkpoint in the immune response." (PMID 32149101, 2020). "These tumor-associated neutrophils interact with CD47, inhibiting phagocytosis by macrophages and increase inflammation." (PMID 35582213, 2020). "Dysregulation of CD47, therefore, affects tumor-associated efferocytosis and represents a promising therapeutic strategy." (PMID 32370748, 2020).